ADAMTSL2 (ADAMTS like 2)
Synonyms: ADAMTSL-2; KIAA0605; GPHYSD1
Tractability: Antibody: UniProt places it where antibodies can reach, with high confidence; UniProt predicts a signal peptide or a membrane-spanning region; its Gene Ontology location is reachable by antibodies, with medium confidence.
Gene: Protein-coding gene on chromosome 9 (133,532,164 to 133,575,522, forward strand). Ensembl gene ENSG00000197859.
Subcellular location: Secreted
Subcellular location (Human Protein Atlas): Vesicles; Predicted to be secreted
Pathways (Reactome):
Disease: Defective B3GALTL causes PpS
Metabolism of proteins: O-glycosylation of TSR domain-containing proteins
Gene Ontology:
Molecular function: protein binding; metalloendopeptidase activity; microfibril binding
Biological process: negative regulation of transforming growth factor beta receptor signaling pathway; extracellular matrix organization
Cellular component: extracellular matrix; extracellular region
Genetic constraint (gnomAD): Loss-of-function variants: 55 observed, 101.34 expected, observed/expected ratio (o/e) 0.54, 90% interval 0.44 to 0.68. The upper end of that interval is the gene's LOEUF score, 0.68, which puts it in group 2 of 6, group 1 being the genes least tolerant of losing a copy. Missense variants: 1,182 observed, 1,288.1 expected, observed/expected ratio (o/e) 0.92, 90% interval 0.87 to 0.96. Synonymous variants: 572 observed, 534.08 expected, observed/expected ratio (o/e) 1.07, 90% interval 1 to 1.15.
Homologues: Orthologues: chimpanzee ADAMTSL2 (99% identical), macaque ADAMTSL2 (98% identical), dog ADAMTSL2 (91% identical), pig ADAMTSL2 (91% identical), rat Adamtsl2 (89% identical), mouse Adamtsl2 (89% identical), guinea pig ADAMTSL2 (88% identical), tropical clawed frog ADAMTSL2 (71% identical), zebrafish adamtsl2 (57% identical). Paralogues in human: THSD4 (26% identical), ADAMTS7 (24% identical), ADAMTS18 (24% identical), ADAMTSL4 (24% identical), ADAMTS12 (23% identical), ADAMTS20 (23% identical), ADAMTS9 (23% identical), ADAMTS16 (23% identical), PAPLN (22% identical), ADAMTSL3 (22% identical), ADAMTSL1 (21% identical), ADAMTS6 (21% identical), and 13 more.